SFRP1 (secreted frizzled related protein 1)
Diseases named in the same sentence as SFRP1 in open-access papers (continued):
Sharing a sentence is not in itself a finding about the gene and the disease.
colon carcinoma (29 papers, 2006 to 2024). "Loss or downregulation of sFRP1 expression plays an important role in the development and progression of various cancer, including colon cancer, lung cancer, and HCC." (PMID 32293507, 2020). "Secreted Frizzled-related protein-1 can also inhibit β-catenin/Tcf activity in colon cancer cells with mutations in APC that stabilise β-catenin." (PMID 19277043, 2009). "On the other hand, several studies in colon cancer show that the canonical Hedgehog pathway inhibits Wnt by regulating the expression of SFRP1 via its effector proteins, GLI1 and GLI2." (PMID 38474826, 2024). "It is possible that SFRP4 is targeted by genetic alterations as it has been described for SFRP1 in colon cancers." (PMID 38993819, 2024). "The Wnt/β-catenin signaling pathway-mediated effect of miR-144-3p in colon carcinoma was finally validated through the targeting of SFRP1." (PMID 37859826, 2023). "In order to validate the promotion of migration abilities in colon carcinoma cells by miR-144-3p through regulation of SFRP1, a functional rescue experiment was conducted." (PMID 37859826, 2023). "The qPCR were used to detect the expression of SFRP1 in 60 patients of colon carcinoma and paracancerous tissue samples." (PMID 37859826, 2023). "We have reported a study on the mechanism of miR-144-3p/SFRP1 molecular axis in colon carcinoma through activating the Wnt/β-catenin signaling pathway for the first time." (PMID 37859826, 2023). "In this study, we aim to elucidate the impact and mechanism of miR-144-3p in modulating the Wnt/β-catenin signaling pathway by targeting SFRP1, thereby offering novel biomarkers for the diagnosis, prognosis, and molecular targeted therapy of colon carcinoma." (PMID 37859826, 2023). "The results of dual-luciferase reporter gene assay revealed that miR-144-3p targeted SFRP1, and rescue experiment was carried out and its results indicated that miR-144-3p increased colon carcinoma cells' migration through targeting SFRP1." (PMID 37859826, 2023). "First, our result showed that patients with SFRP2 hypermethylation or co-hypermethylation of SFRP1 and SFRP2 had a lower risk of death in groups of ≥45 years old, male, colon cancer and TNM staging III-IV in traditional univariate and multivariate Cox." (PMID 31830937, 2019). "For colon cancer, patients with promoter hypermethylation of SFRP1 or co-hypermethylation of SFRP1 and SFRP2 had higher overall survival." (PMID 31830937, 2019). "They reported that the inhibition of LSD1 in human colon carcinoma cells by biguanide and bisguanidine polyamine analogues resulted in a re-expression of aberrantly silenced genes, including SFRP1, SFRP4, SFRP5, and GATA5." (PMID 23922913, 2013). "The expression pattern of these sPLA2s appeared to be linked respectively to the overexpression of interleukin-8, defensin α6, survivin and matrilysin, and downregulation of SFRP-1 and RLPA-1, all these genes being associated to colon cancer." (PMID 18212756, 2008). "Concerning the soluble activators of FZD, previous studies have shown the common downregulation of sFRP1 due to promoter hypermethylation in HCC as well as in colon cancer." (PMID 18577996, 2008). "Besides, miR-144-3p encourages colon carcinoma cell proliferation, migration and invasion through the target gene SFRP1." (PMID 37859826, 2023). "The downregulation of the signal suppressor protein SFRP1 may contribute to the accumulation of β-catenin in the cytoplasm and nucleus of colon carcinoma, as well as the activation of the Wnt/β-catenin signaling pathway." (PMID 37859826, 2023). "The present study aimed to investigate the involvement of miR-144-3p, SFRP1, and the Wnt/β-catenin signaling pathway in colon carcinoma at multiple levels (i.e., tissue level, cell level, and cellular function) to elucidate their underlying mechanisms of action." (PMID 37859826, 2023).
colon carcinoma (continued). "Similarly, in colon cancer, a subpopulation of CAFs that overexpress Sfrp1/2 have been identified, promoting greater rates of malignancy in intestinal tumors." (PMID 36968194, 2023). "In addition to breast tumors that have low sFRP1 levels, sFRP1 suppression has been described in colon tumors, ovarian tumors, bladder tumors and prostate tumors." (PMID 19473496, 2009). "We have shown previously that the silencing of the SFRP1 and -2 genes is important for aberrant activation of the Wnt pathway in colon cancer cells, and their re-introduction into such cells in which the genes are silenced causes sharp down-regulation of Wnt pathway function and apoptosis." (PMID 16596166, 2006). "Finally, down-regulation of SIRT1 in breast and colon cancer cell lines leads to re-expression of the Wnt pathway inhibitors, SFRP1 and SFRP2 (Secreted Frizzled-like Proteins 1 and 2), which are frequently inactivated in human cancers through epigenetic means, as discussed in greater detail below." (PMID 23799088, 2013). "- Overexpression of miR-766 contribute to inhibition of colon cancer development by decreasing methylation of tumor suppressor genes including DKK2, WIF1, SFRP1, and SFRP2." (PMID 37205191, 2023). "For colon cancer patients, SFRP2 hypermethylation patients and co-hypermethylation of SFRP1 and SFRP2 patients had a significantly favorable outcome through multivariate Cox regression, PS-1 and PS-2 analysis." (PMID 31830937, 2019). "When we tested an additional known methylated gene, SFRP1, in combination with OSMR the sensitivity of the assay increased; 60% (12/20) of colon cancers were detected in stool DNA with perfect specificity (P<0.001)." (PMID 19662090, 2009). "Moreover, the extracellular Wnt antagonists Sfrp1 and Sfrp2 are upregulated by Shh-Gli signalling in different experimental systems and nuclear accumulation of the Wnt transducer β-catenin and the Shh transducer Gli1 are inversely correlated in a human colon cancer cell line." (PMID 19732418, 2009). "A previous study reported that inhibition of LSD1 with polyamine analogs not only increased global levels of H3K4 methylation, but also H3K9ac, an epigenetic mark at active promoters, at the promoters of SFRP1, SFRP5, SFRP5 and GATA5 in human colon carcinoma cells." (PMID 38971831, 2024). "SFRP1, 2, 5 genes are frequently silenced by promoter hypermethylation in human CRC, a high percentage of DNA methylation in SFRP5 gene promoter has been detected by us in AOM-induced colon tumors (unpublished data)." (PMID 23717604, 2013). "SFRP-1 and the SFRP-like molecule V3Nter can inhibit Wnt signaling and expression of the β-catenin target genes - cyclin D1 and c-myc, finally inhibiting tumor growth of β-catenin-activated tumor cells such as colon cancer SW480 and HCT-116 cells." (PMID 23469066, 2013). "The regulation of SFRP1 by miR-144-3p was investigated using a dual-luciferase reporter system, and a rescue experiment was conducted to further elucidate whether miR-144-3p promotes the migration of colon carcinoma cells through targeting SFRP1 or not." (PMID 37859826, 2023). "This might involve the upregulation of WNT inhibitors (e.g. DKK1 and SFRP1) as observed in metastatic vs. non-metastatic colon cancer patients, but also oncogene-mediated increases in GLI function and cell-intrinsic metastatic reprogramming." (PMID 31253868, 2019). "Here, we show that Qc reduces cell viability and induces apoptosis in HCT116 and HT-29 colon cancer cells, by upregulating negative modulators of proliferation pathways such as Sprouty2, PTEN and SFRP1." (PMID 37627542, 2023).
prostate carcinoma (26 papers, 2004 to 2025). A carcinoma that arises from epithelial cells of the prostate gland. "The results presented in this article prove that SFRP1 reduced the susceptibility of prostate cancer cells to bicalutamide." (PMID 36968194, 2023). "As SFRP1 downregulation has been linked to epigenetic inactivation in prostate cancer, further studies to investigate the therapeutic benefit of using DNA methylation drugs for the treatment of advanced prostate cancer is needed." (PMID 35204808, 2022). "Genistein treatment in prostate cancer significantly down-regulated miR-1260b and caused subsequent up-regulation of its targets sFRP1 and Smad4 by DNA demethylation and histone modifications, which caused a suppression of prostate cancer cells." (PMID 34289845, 2021). "Loss of expression of the genes WNT Inhibitory Factor 1 (WIF1) and Secreted Frizzled Related Protein 1 (sFRP1), due to promotor methylation inhibits Wnt signaling and is associated with prostate cancer." (PMID 35201496, 2021). "The loss of SFRP1 expression is associated with the early development of colorectal cancer (CRC) as well as prostate cancer, and is linked with disease recurrence in renal cell cancer." (PMID 32074995, 2020). "In addition we performed RT-qPCR and western blot analysis to compare SFRP1 expression between normal fibroblasts (NF), cancer-associated fibroblasts (CAFs), LNCaP, and DU-145 prostate cancer cell lines." (PMID 36968194, 2023). "This is the first study to demonstrate that exogenous SFRP1 signaling is implicated in the promotion of a stem cell phenotype in prostate cancer epithelial cells and this may be mediated by the activation of the WNT pathway." (PMID 36968194, 2023). "We evaluated whether SFRP1 may modulate prostate cancer stem cell populations and features associated with stem cells in PCa cells." (PMID 36968194, 2023). "The aim of this study was to examine whether the expression of SFRP1 and β-catenin is associated with the clinical-pathologic features of patients with prostate cancer (PCa), and to evaluate their potential roles as predictive and prognostic biomarkers." (PMID 25719802, 2015). "In another study, it has been reported that genistein increases the expression of tumor suppressors sFRP1 and Smad4 in prostate cancer cells by reducing the expression of miR-1260b and also DNA methylation." (PMID 40718456, 2025). "But in the researches of prostate cancer cells in vitro, the overexpression of SFRP1 promotes the growth of BPH1, whereas over-expression of SFRP4 or SFRP3 decreases the proliferation of human PC3 cells." (PMID 36991319, 2023). "In this investigation, we confirm that SFRP1 is suppressed in prostate cancer epithelial cell lines, and expressed in CAFs, we have also demonstrated that SFRP1 was secreted to the media by CAFs." (PMID 36968194, 2023). "In the present study, we explored the role of exogenous SFRP1 on the regulation of stem cell phenotype in prostate cancer." (PMID 36968194, 2023). "It has been reported that one of the mediators of stromal epithelial signaling is the SFRP1 protein which mediates stromal epithelial communication in prostate cancer." (PMID 36968194, 2023). "In the present study, we explored the role of exogenous SFRP1 on the stem cell phenotype in prostate cancer." (PMID 36968194, 2023). "SFRP1 expression has also been shown to be regulated by microRNAs in prostate cancer, such as miR1301-3p and miR1260b." (PMID 35204808, 2022). "In androgen-sensitive prostate cancer cells, SFRP1 has been shown to inhibit AR transcriptional activity independently of Wnt/β-catenin signaling." (PMID 35204808, 2022). "SFRP1 expression inversely correlates with β-catenin in prostate cancer, where low expression of SFRP1 predicts a worse outcome, and SFRP1 downregulation has been linked to epigenetic inactivation." (PMID 35204808, 2022).
prostate carcinoma (continued). "In prostate cancer cells, the expression of sFRP1 and Smad4 are down-regulated by increased expression of miR-1260b, resulting in cell proliferation, invasion, migration and TCF reporter activity." (PMID 34289845, 2021). "The inactivation of SFRP1 leads to the uncontrolled AR activation, which is involved in the pathogenesis of prostate cancer." (PMID 32074995, 2020). "Silencing of miR-1260b in prostate cancer cells enhanced the expression of sFRP1 and Smad4 and decreased cellular proliferation, invasion, and migration." (PMID 32523124, 2020). "SFRP1 which functions as modulators of Wnt signalling is a favourable predictive and prognostic biomarker for prostate cancer." (PMID 32564237, 2020). "The expression of SFRP1 is low in many models of prostate cancer cells, has been proposed this due a methylation-independent mechanism and even it has been proposed SFRP1 as a possible biomarker in the diagnosis of PCa." (PMID 32694934, 2020). "In a plethora of solid tumors, including colorectal cancer, ovarian cancer, prostate cancer and lung cancer, it has been shown that SFRP1 is inactivated by promoter hypermethylation." (PMID 25033833, 2014). "We investigated the function of sFRP1 in androgen-dependent prostate cancer and found that sFRP1 inhibited androgen receptor (AR) transcriptional activity." (PMID 19277043, 2009). "Because sFRP1 is best known as a Wnt antagonist, it is plausible that it represses AR by sequestering endogenous Wnt ligands secreted by prostate cancer cells." (PMID 19277043, 2009). "To summarise, we have shown that sFRP1 represses AR transcriptional activity and, as a result, inhibits proliferation of androgen-dependent prostate cancer cells and that the CRD is mainly responsible for both of these effects." (PMID 19277043, 2009). "Secreted Frizzled-related protein-1 expression is downregulated in many cancers including prostate cancer." (PMID 19277043, 2009). "Taken together, these observations highlight the function of β-catenin-independent Wnt signalling in the control of AR activity and provide one explanation for sFRP1 downregulation in prostate cancer." (PMID 19277043, 2009). "Furthermore, SFRP1 promoted prostate cancer stem cell (PCSC) properties in vitro, including tumorsphere formation, migration, bicalutamide resistance, and decreased apoptosis." (PMID 36968194, 2023). "In prostate cancer, it promotes cell expansion by targeting SFRP1 and GSK3β." (PMID 33363159, 2020). "The cysteine-rich domain of SFRP1 interacts with frizzled receptors in prostate cancer cells, and the SFRP1/frizzled complexes activate a signal that may lead to the repression of downstream signalling." (PMID 32764696, 2020). "SFRP1 up levels was found in normal prostate tissues but down levels in prostate cancer samples." (PMID 32694934, 2020). "Interestingly, the cysteine-rich domain of sFRP1 interacted with Frizzled receptors expressed in prostate cancer cells, suggesting that sFRP1/Frizzled complexes activate a signal that leads to repression of AR." (PMID 19277043, 2009). "Therefore, it is important to consider the possibility that loss of sFRP1 affects signalling pathways other than those mediated by β-catenin/TCF, and that these drive prostate cancer cell proliferation." (PMID 19277043, 2009). "Because the sFRP1 CRD competes with Frizzled receptors for binding to Wnts, we hypothesised that sFRP1 represses AR by antagonising autocrine Wnt signals in prostate cancer cells." (PMID 19277043, 2009). "Likewise, an aberrant gain of the repressive mark H3K27me3 could decrease the expression of SFRP1 gene in addition to DNA hypermethylation in prostate cancer cell line." (PMID 28422739, 2017). "In contrast to breast tumor stroma, the stromal reaction to invasive prostate cancer displayed fewer genes involved in tissue remodeling but a higher number of genes belonging to defined signaling pathways, including members of the Wnt signaling pathway (SFRP1, RSPO3)." (PMID 21611158, 2011).
prostate carcinoma (continued). "miR1260b is reported to regulate two tumor suppressor genes, sFRP1 and SMAD4, in prostate cancer through epigenetic mechanisms, and to also extensively participate in arthritis, osteogenic differentiation, and Alzheimer's disease." (PMID 38658973, 2024). "Secreted Frizzled-related protein-1 was reported to inhibit RANKL-dependent osteoclast formation and RANKL is found in prostate cancer cells, where it is thought to mediate the effects of prostate tumour cells on osteoclastogenesis in vivo." (PMID 19277043, 2009). "Indeed, primary human CD105+ CAFs show increased expression of secreted frizzled related protein 1 (SFRP1) compared to normal CAF lines, and have been shown to promote neuroendocrine differentiation in prostate cancer cells in vitro." (PMID 36671452, 2022). "Later, the SFRP1 mRNA expression was investigated in non-malignant prostate cells and prostate cancer cells." (PMID 32694934, 2020). "We conducted RT–PCR analysis of sFRP family gene expression using cell lines derived from normal prostate and prostate cancer and confirmed previous reports that sFRP1 expression is reduced in prostate cancer cells (data not shown)." (PMID 19277043, 2009). "Six of these loci had previously been reported to be hypermethylated in prostate cancers, whereas ASC1 and SFRP1 had been reported as frequently hypermethylated in other cancers, but not been studied in prostate cancer before." (PMID 15292941, 2004). "Although we found that the CRD of sFRP1 is able to interact with each of four frizzled family members that are highly expressed in AR-expressing prostate cancer cell lines, sFRP1 repression of AR was not rescued by PTX treatment, indicating that G proteins are not involved in this phenomenon." (PMID 19277043, 2009). "Importantly, sFRP1 inhibited colony formation of LNCaP cells but not of LNCaP-r cells, thus linking the growth inhibitory effects of sFRP1 to androgen-dependent proliferation of prostate cancer cells." (PMID 19277043, 2009).